SLC7A11 (solute carrier family 7 member 11)
Diseases named in the same sentence as SLC7A11 in open-access papers (continued):
Sharing a sentence is not in itself a finding about the gene and the disease.
cancer (continued). "Because mTORC1 regulates the ERO1α/SLC7A11 signaling network in multiple human cancer cell lines in vitro, we predicted that this signaling regulation should also exist in human tumors in vivo." (PMID 38610018, 2024). "IR can induce SLC7A11 and GPX4 upregulated as an adaptive response to safeguard cells against ferroptosis and contribute to radioresistance, suggesting that inhibiting SLC7A11 or GPX4 sensitizes radioresistant cancers to IR." (PMID 38453898, 2024). "In most cancer cells, cysteine is acquired through the uptake of extracellular cystine via the amino acid transporter SLC7A11, which is then reduced to cysteine intracellularly, ultimately fueling GSH biosynthesis." (PMID 38842940, 2024). "Adding to the complexity, interferon-gamma (IFNG/IFN-γ), which is released from CD8+ T cells, downregulates the expression of SLC7A11, effectively promoting ferroptosis induction in HT-1080 and B16 cancer cells." (PMID 39090114, 2024). "SLC7A11 exerted multiple pathological effects in inflammatory disease and cancers, although SLC7A11 resisted ferroptosis." (PMID 39457614, 2024). "The results showed that SLC7A11 expression was positively correlated with the individual cancer stages of LUAD." (PMID 38561419, 2024). "Contrary to the oncogenic implications outlined earlier, the upregulation of SLC7A11 can also induce apoptotic cell death in cancer cells under conditions." (PMID 39040097, 2024). "The upregulation of SLC7A11 reduces methionine-dependence in cancer cells, a common feature among cancer cells." (PMID 39606232, 2024). "Cancer cells with high SLC7A11 expression exhibit increased sensitivity under limited glucose conditions, leading to an increased dependence of cancer cells on glucose." (PMID 39350768, 2024). "SLC7A11 is a cystine/glutamate antiporter, primarily responsible for amino acid transport across the plasma membrane, and it plays a crucial role in cancer cell survival." (PMID 38994937, 2024). "Through screening efforts, novel inhibitors of SLC7A11 have been designed with the aim of promoting ferroptosis and ultimately eliminating cancer cells." (PMID 39195490, 2024). "In cancer cells, the overexpression of SLC7A11 promotes cystine uptake, thereby increasing resistance to oxidative stress and ferroptosis." (PMID 39590840, 2024). "Cancer cells must undergo metabolic reprogramming to provide high levels of glutamine to SLC7A11 to supply sufficient GSH for its function." (PMID 38674143, 2024). "A primary pathway for inducing ferroptosis in cancer cells involves nutrient deprivation of the amino acid cystine or the pharmacological inhibition of SLC7A11." (PMID 38844964, 2024). "By regulating the methylation status of SLC7A11, there exists an opportunity to modulate disulfidoptosis activity in tumors, thereby aiming to improve the outcomes of cancer patients." (PMID 38397869, 2024). "In cancer cells, BRCA1-associated protein 1 (BAP1) removes monoubiquitin from ubiquitinated H2A at lysine 119 (H2Aub) on the SLC7A11 promoter, thereby suppressing its expression in cells treated with erastin and activating ATF4." (PMID 39595619, 2024). "This amino acid is provided to cancer cells in the form of cystine via the transporter xCT/SLC7A11, which is upregulated in cancer cells." (PMID 38339256, 2024). "For instance, in cancer cells, altered metabolism often leads to glucose insufficiency, which can trigger disulfidptosis in cells with high SLC7A11 expression." (PMID 38886311, 2024).
cancer (continued). "We then found that after MLN4924 treatment, SLC7A11 levels were remarkably increased in time- and dose-dependent manners in multiple lines of cancer cells, while the SLC3A2 levels were increased moderately in a cell line–dependent manner." (PMID 38959043, 2024). "Disulfidptosis was recently reported to be caused by abnormal disulfide accumulation in cells with high SLC7A11 levels subjected to glucose starvation, suggesting that targeting disulfidptosis was a potential strategy for cancer treatment." (PMID 38584831, 2024). "The occurrence of disulfidptosis often happens in cells with high SLC7A11 expression, allowing the accumulation of cystine within cells and then exposes a targetable metabolic vulnerability in cancer." (PMID 39868374, 2024). "Accordingly, the amino acid transporter SLC7A11, which provides the limiting amino acid cysteine for glutathione synthesis, is an important controller of ferroptosis in cancer cells." (PMID 38891084, 2024). "The qRT-PCR results demonstrated a significant upregulation of SLC7A11 expression in the cancer cell lines compared to their corresponding normal counterparts." (PMID 38397869, 2024). "SASP itself is a known inducer of ferroptosis; when used in combination with vorinostat it can further promote this process by targeting SLC7A11 expression which is related to cancer cell insensitivity to HDAC inhibitors." (PMID 39193375, 2024). "As disulfidptosis is a new type of cell death that occurs in SLC7A11high cells, we screened cancer types with a high SLC7A11 expression." (PMID 38540687, 2024). "The high expression of SLC7A11 in cancer cells results in excessive uptake of cystine into the cell, the reduction process of which consumes large amounts of NADPH (glucose metabolite) and induces cell-specific death by inhibiting glucose transporter." (PMID 38388539, 2024). "SLC7A11 has been found to be overexpressed in many types of human cancers, and specifically inhibiting SLC7A11 shows a high level of responsiveness." (PMID 39807126, 2024). "In cancer cells with abnormal SLC7A11 expression, high rates of cystine uptake and reduction to cysteine, combined with glucose starvation, deplete the NADPH pool." (PMID 38862242, 2024). "PTEN loss is associated with increased expression of the SLC7A11, leading to higher cystine import, elevated GSH synthesis, and resistance to ferroptosis in many cancer cell lines." (PMID 38562143, 2024). "Activation of NRF2 axis in cancer cells triggers the induction of multiple anti-ferroptotic genes, including SLC7A11, ATP binding cassette subfamily C member 5 (ABCC5), metallothionein 1G (MT1G), FSP1, CBS, and superoxide dismutase 2 (SOD2)." (PMID 39624080, 2024). "Second, T alters the dependence on glucose in SLC7A11 high cancer cells by limiting the uptake of glucose with GLUT inhibitors." (PMID 37598126, 2023). "Resveratrol (RES) can inhibit the interaction of HMMR and SLC7A11 to mediate cancer cell ferroptosis." (PMID 38288118, 2023). "Recent studies have indicated a negative correlation between the transcription levels of CBS and SLC7A11 (xCT) in cancer cell lines from the Cancer Cell Line Encyclopedia31 across various cancer types." (PMID 37381723, 2023). "Our current data further suggest that SLC7A11-high cancer cells would be positively selected in primary tumors but negatively selected in metastasized tumors." (PMID 37339981, 2023). "SLC7A11 is highly expressed in human tumors, and its high expression can prevent ferroptosis in cancer cells." (PMID 37007068, 2023).
cancer (continued). "Intriguing correlations between SLC7A11 and various immune cells in cancer have also been reported, hinting at SLC7A11s role in modulating T-cell functionality in lung adenocarcinoma." (PMID 37892851, 2023). "Inactivation of SLC7A11 or GPx4 with FINs can sensitize radiation-resistant cancer cells and xenografts to IR." (PMID 37007068, 2023). "It has been reported that SLC7A11 is closely associated with cancer ferroptosis induced by lipid peroxidation, and OTUB1 improves SLC7A11 stability by removing the ubiquitin modification." (PMID 37190313, 2023). "Inhibition of glucose transporter proteins (GLUT) has shown therapeutic efficacy against SLC7A11-high expressing cancer cells by inducing disulfidptosis." (PMID 37946181, 2023). "The supplementation of cystine also induced disulfidptosis in cancer cells with SLC7A11 low expression, accompanied by intracellular NADPH depletion, aberrant disulfide frormation in actin cytoskeleton and F-actin contraction." (PMID 37318660, 2023). "For example, data from The Cancer Genome Atlas have revealed that SLC7A11 plays a role in the radioresistance of gliomas." (PMID 37488128, 2023). "In contrast, cancer cells are more dependent on SLC7A11-mediated cysteine uptake for cysteine acquisition and maintenance of redox homeostasis than normal tissues." (PMID 36874967, 2023). "On the one hand, SLC7A11 overexpression has been shown to correlate with or functionally promote resistance to various anti-cancer drugs, such as cisplatin, gemcitabine, and MAPK pathway inhibitors." (PMID 36874967, 2023). "This phenomenon extended the functional layers of SLC7A11 regulated by post‐translational modifications, and highlighted the importance of lncRNA in cancer metabolic reprogramming and ferroptosis mediated by SLC7A11." (PMID 37337470, 2023). "SLC7A11 is the core target for ferroptosis regulation; the overexpression of which dictates downregulated sensitivity to ferroptosis in cancer cells." (PMID 36846715, 2023). "In cancer cells, silencing SLC7A11 makes them more sensitive to ferroptosis induced by erastin, while overexpressing SLC7A11 makes them more resistant to it." (PMID 36935924, 2023). "As a result of its absence from normal physiology and the high level of expression it displays in cancer, SLC7A11 is a promising candidate for use as a cancer therapeutic target." (PMID 37598126, 2023). "The results of this study provide a new direction for the development of cancer therapy targeting the SLC7A11/GPX4 pathway." (PMID 37266741, 2023). "In our study of the correlation between the Cancer–Immunity Cycle and SLC7A11, we also observed similar phenomena." (PMID 38132439, 2023). "The Cancer Genome Atlas database analysis also showed higher SLC7A11 expression in ADC and SCC tissue than in adjacent tissues." (PMID 37056388, 2023). "The solute carrier family 7 member 11 (SLC7A11) is widely overexpressed in cancers and is well-known for its role in maintaining intracellular glutathione levels and preventing oxidative stress-induced cell death, such as ferroptosis." (PMID 37238995, 2023). "By contrast, Fer-1 rescued the alterations in markers of ferroptosis (GPX4 and SLC7A11) and cancer cell stemness (Oct4 and Sox2) induced by JYQHD." (PMID 37700383, 2023). "In contrast, in cancer cells with high SLC7A11 overexpression, drastic accumulation of intracellular cystine and other disulfide molecules under H2O2 treatment overrides any beneficial effect of GSH and leads to redox system collapse and rapid cell death." (PMID 37339981, 2023). "System xc- is a cystine/glutamate antiporter, and the inhibition of its activity by erastin in cancer cells triggers ferroptosis; SLC7A11 is a key component of system xc-." (PMID 36846715, 2023).
cancer (continued). "In cancer cells overexpressing SLC7A11, glutamine import and the activity of glutaminase must be elevated to compensate for glutamate export and glutamine addiction, which is acquired." (PMID 38203246, 2023). "Addressing this question will help understand the metabolic nature of disulfide stress–induced cell death in SLC7A11-overexpressing cancer cells and identify therapeutic strategies to target SLC7A11-overexpressing cancers." (PMID 37339981, 2023). "SLC7A11 is a functional component of the system xc-, which is overexpressed in various human cancers." (PMID 37978473, 2023). "The suppressor of cytokine signaling 2 (SOCS2) promotes ferroptosis and radiosensitization in cancer by enhancing the ubiquitination of SLC7A11." (PMID 37714846, 2023). "Several pharmacologic inhibitors of SLC7A11, such as erastin and sulfasalazine, can increase the sensitivity of cancers to radiotherapy or re-sensitize radioresistant cancer cells." (PMID 37714846, 2023). "Reduction of available glucose in SLC7A11 high expressing cancer cells induces disulfide bond stress, leading to rapid cell death." (PMID 36874967, 2023). "Previously, we and others showed that, in SLC7A11-overexpressing cancer cells, the reduction of cystine to cysteine consumes large amounts of NADPH." (PMID 37339981, 2023). "To validate our findings, we examined the expression profile of SLC7A11 in several clinical variables using GEO datasets, which confirmed its higher expression in advanced clinicopathological stages and cancer tissues." (PMID 37427103, 2023). "GPX4 acts as a downstream of SLC7A11, and its expression is also increased, which contributes to cancer resistance to chemotherapy-induced ferroptosis." (PMID 37266741, 2023). "The significant accumulation of cystine is highly toxic to cells, compelling cancer cells with high levels of SLC7A11 to reduce cystine to cysteine, resulting in substantial consumption of nicotinamide adenine dinucleotide phosphate (NADPH)." (PMID 38116315, 2023). "Here we report a surprising finding that, whereas moderate overexpression of SLC7A11 is beneficial for cancer cells treated with H2O2, a common oxidative stress inducer, its high overexpression dramatically increases H2O2-induced cell death." (PMID 37339981, 2023). "Hypoxia increases ELAVL1 by HIF-1 upregulation, and ELAVL1 then combines with SLC7A11 to improve the expression of SLC7A11, thereby promoting cancer cells growth by inhibiting ferroptosis." (PMID 37458878, 2023). "The upregulated ferroptosis genes among all cancers were SLC7A11, FANCD2, CARS, SLC1A5, and RPL8, while the expression of NCOA4 was downregulated." (PMID 38203246, 2023). "The significance of disulfidptosis lies in its potential as a target for cancer therapy, especially in cancer cells with high expression of SLC7A11." (PMID 37946181, 2023). "The induction of ferroptosis is an attractive strategy for cancer therapy because a single inhibitor of GPX4 or SLC7A11 can markedly induce ferroptosis in cells." (PMID 37714840, 2023). "In this study, we discovered that NAT10 depletion induces ferroptosis in cancer cells through the SLC7A11/GSH/PLOOH axis." (PMID 37237981, 2023). "Although the key gene SLC7A11, which is involved in disulfidptosis, shows significant high expression in most tumors, the relationship between disulfidptosis and cancer is insufficiently understood." (PMID 37845218, 2023). "The cystine transporter SLC7A11 protects cancer cells from oxidative stress by supporting glutathione synthesis." (PMID 37339981, 2023). "Targeting SLC7A11 has been explored to be an effective approach to eradicate cancer cells by triggering ferroptosis." (PMID 37087976, 2023).
cancer (continued). "SLC7A11, the catalytic subunit of the xCT system, is upregulated in several cancers and is an indicator of antiporter xCT activity." (PMID 37718459, 2023). "We conducted a comprehensive pan-cancer analysis of SLC7A11 to unveil the potential involvement of disulfidptosis in cancer." (PMID 38132439, 2023). "SLC7A11, as a main BAP1 target gene in ferroptosis of cancers cell, is regulated by BRCA1-associated protein 1 (BAP1) on epigenetic mechanism." (PMID 37250891, 2023). "The relationship between the oncogene c-myc and glutamine transporters SLC7A5/SLC7A11 has been investigated in cancer research." (PMID 37649668, 2023). "For instance, to mitigating the damaging effects of ROS, cancer cells upregulate the expression of SLC7A11, a cystine-glutamate antiporter, increase the import of cystine to generate cysteine and glutathione." (PMID 37864127, 2023). "The combination of ferroptosis inducer targeting SLC7A11 and radiotherapy synergistically induces ferroptosis and improves the sensitivity of cancer cells to radiotherapy." (PMID 37714846, 2023). "Information on SLC7A11 expression and its impact on prognosis was obtained from the cancer genome atlas and gene expression omnibus databases." (PMID 37880315, 2023). "Solute Carrier Family 7 member 11 (SLC7A11) is a key gene involved in redox regulation in cancer cells and codes for the multipass transmembrane protein xCT." (PMID 37770957, 2023). "CircRPPH1 as a miR-375 sponge positively regulates SLC7A11 expression and has been shown to be a direct target of miR-377 in cancer, thereby regulating cellular ferroptosis." (PMID 37152286, 2023). "The cystine transporter solute carrier family 7 member 11 (SLC7A11; also called xCT) protects cancer cells from oxidative stress and is overexpressed in many cancers." (PMID 37339981, 2023). "Extensive research has consistently demonstrated the overexpression of SLC7A11 in several cancer types, including colorectal cancer, ovarian cancer, lung cancer, and ESCC." (PMID 37564206, 2023). "Previously, we showed that glucose starvation in cancer cells with moderate or high overexpression of SLC7A11 resulted in the marked accumulation of intracellular cystine and other disulfide molecules as well as NADPH depletion, and rapid cell death." (PMID 37339981, 2023). "We conducted a comprehensive pan-cancer analysis of SLC7A11, a gene that plays a significant role in disulfidptosis." (PMID 38132439, 2023). "By upregulating the expression of SLC7A11 through a variety of mechanisms, cancer cells enhance their antioxidant defense ability and inhibit ferroptosis." (PMID 37822721, 2023). "Many cancer cells take up extracellular cysteine through the glutamate/cysteine transporter system, solute carrier family-7 member-11 (SLC7A11)." (PMID 37190313, 2023). "Blocking SLC7A11 can exert cytotoxic effects and reverse the low therapeutic sensitivity of cancer stem cells (CSCs) to DOX via a ferroptosis mechanism." (PMID 37344500, 2023). "The cystine/glutamate antiporter SLC7A11 (also commonly known as xCT), which plays functions in importing cystine for glutathione biosynthesis and antioxidant defense, was overexpressed in multiple human cancers." (PMID 36851605, 2023). "SLC7A11 is overexpressed in several cancer types and promotes cystine uptake and glutathione biosynthesis, which resulted in protection from oxidative stress and ferroptosis." (PMID 36106577, 2023). "Pan-cancer analysis revealed that, compared with that in the normal tissues, the expression level of SLC7A11 was up-regulated in several types of cancers." (PMID 37713821, 2023).